LZTR1 (leucine zipper like post translational regulator 1)
Description:
Substrate-specific adapter of a BCR (BTB-CUL3-RBX1) E3 ubiquitin-protein ligase complex that mediates ubiquitination of Ras GTPases (M-Ras/MRAS, K-Ras/KRAS, N-Ras/NRAS and H-Ras/HRAS) and Ras-like protein RIT1. Acts as a negative regulator of RAS-MAPK signaling by controlling Ras levels and decreasing Ras association with membranes.
Synonyms: LZTR-1; BTBD29; NS10; NS2; SWNTS2
Tractability: PROTAC: ubiquitination databases record sites on it; its protein half-life has been measured.
Gene: Protein-coding gene on chromosome 22 (20,982,223 to 20,999,035, forward strand). Ensembl gene ENSG00000099949.
Subcellular location: Endomembrane system; Recycling endosome; Golgi apparatus
Subcellular location (Human Protein Atlas): Nucleoplasm; Centrosome; Cytosol
Gene Ontology:
Molecular function: protein binding; small GTPase binding; ubiquitin-like ligase-substrate adaptor activity
Biological process: negative regulation of Ras protein signal transduction; proteasome-mediated ubiquitin-dependent protein catabolic process; protein ubiquitination
Cellular component: Cul3-RING ubiquitin ligase complex; endomembrane system; Golgi apparatus; recycling endosome; recycling endosome membrane
Genetic constraint (gnomAD): Loss-of-function variants: 243 observed, 100.58 expected, observed/expected ratio (o/e) 2.42. Missense variants: 1,186 observed, 1,136.3 expected, observed/expected ratio (o/e) 1.04, 90% interval 0.99 to 1.1. Synonymous variants: 484 observed, 470.26 expected, observed/expected ratio (o/e) 1.03, 90% interval 0.95 to 1.11.
Gene-disease validity (ClinGen):
ClinGen rates the evidence that LZTR1 causes each of these diseases.
Noonan syndrome (autosomal dominant; autosomal recessive): Definitive. Noonan Syndrome (NS) is characterized by short stature, typical facial dysmorphism and congenital heart defects.
Homologues: Orthologues: chimpanzee LZTR1 (99% identical), macaque LZTR1 (99% identical), guinea pig LZTR1 (97% identical), pig LZTR1 (95% identical), mouse Lztr1 (95% identical), dog LZTR1 (92% identical), rat Lztr1 (91% identical), rabbit LZTR1 (91% identical), zebrafish lztr1 (81% identical), tropical clawed frog lztr1 (80% identical), Drosophila melanogaster Lztr1 (51% identical). Paralogues in human: HCFC1 (18% identical), HCFC2 (13% identical), KLHDC3 (12% identical), FBXO42 (12% identical), KLHDC4 (12% identical), RABEPK (11% identical), KLHDC10 (11% identical), KLHDC1 (11% identical), KLHDC2 (9% identical), KLHDC9 (8% identical).
Diseases named in the same sentence as LZTR1 in open-access papers:
LZTR1 is named in the same sentence as 140 diseases in open-access papers, as found by Europe PMC text mining. Sharing a sentence is not in itself a finding about the gene and the disease. The quoted sentences say what the papers report.
schwannomatosis (66 papers, 2015 to 2026). The least frequent form of the rare genetic disorder neurofibromatosis. "Germline mutations in SMARCB1 are responsible for 48% of familial and 10% of sporadic schwannomatosis cases, while mutations in LZTR1 account for 38% of familial and 30% of sporadic schwannomatosis cases." (PMID 40337438, 2025). "Until the identification of the schwannomatosis-causing genes LZTR1 and SMARCB1, schwannomatosis was mainly identified by clinical criteria and by the exclusion of germline NF2 PVs." (PMID 40794298, 2025). "Germline pathogenic variants in LZTR1 are known to predispose to at least two different conditions, schwannomatosis and Noonan syndrome." (PMID 41284083, 2025). "Schwannomatosis is caused by mutations in the SMARCB1 or LZTR1 genes, which are involved in regulating cell growth and tumor suppression." (PMID 40764996, 2025). "Pathogenic variants in the leucine zipper-like transcriptional regulator 1 gene (LZTR1) have been identified in schwannomatosis and Noonan syndrome." (PMID 39258154, 2024). "Germline LZTR1 variants are reported in Noonan syndrome, either autosomal dominant or autosomal recessive, and in susceptibility to schwannomatosis." (PMID 39062695, 2024). "In fact, pathogenic variants leading to the inactivation of the LZTR1 have been linked to strong activation of the Ras/MAPK pathway leading to diseases such as schwannomatosis and RASopathies." (PMID 38655100, 2024). "Germline and somatic mutations in LZTR1 have been identified in patients with NS, schwannomatosis, and various cancers, including glioblastoma, one of the most challenging cancers to treat." (PMID 39352760, 2024). "The LZTR1-related schwannomatosis variants indexed in the ClinVar database comprise 256 out of a total of 3263 LZTR1 alterations." (PMID 39062695, 2024). "In the literature, LZTR1 LoF variants have been reported in patients with schwannomatosis, glioblastoma, and autosomal recessive NS." (PMID 38654924, 2024). "The NGS analysis using a panel including genes associated with schwannomatosis identified the heterozygous variant NM_006767: c.979delA (p.Ser327Alafs*24) in the LZTR1 gene." (PMID 39062695, 2024). "To better investigate the affected patients, we focused on published cases on Pubmed which comprise 123 eligible schwannomatosis patients with a total of 105 germline LZTR1 variants." (PMID 39062695, 2024). "In contrast, loss-of-function variants of LZTR1, which are commonly associated with schwannomatosis, result in the complete inactivation of the gene." (PMID 39062695, 2024). "Vestibular schwannomas are known to occur in the context of tumour predisposition syndromes NF2-related and LZTR1-related schwannomatosis." (PMID 36546557, 2023). "Germline pathogenic variant in SMARCB1 or LZTR1 strongly suggest the diagnosis of schwannomatosis for patients with a proven schwannoma." (PMID 36440500, 2023). "We have assessed the current evidence available for published LoF LZTR1 variants identified in schwannomatosis patients, many of which were published before the widespread adoption of ACMG/AMP/ACGS classification guidelines." (PMID 35391499, 2022). "We show here that LoF LZTR1 variants are strongly enriched in schwannomatosis patients, but the high frequency of LoF LZTR1 variants in gnomAD data suggest a reduced risk of schwannomas in comparison to other schwannoma predisposing genes." (PMID 35391499, 2022). "LZTR1 variants have been recently described in patients with NS and schwannomatosis, but the association, inheritance pattern and management strategy has not been fully elucidated." (PMID 35840934, 2022). "This means that when LoF LZTR1 variants are detected in patients, more evidence is needed clinically to determine if they are part of the etiology of schwannomatosis." (PMID 35391499, 2022).
schwannomatosis (continued). "Experiments assessing the functionality of missense LZTR1 mutations suggests that schwannomatosis-associated LZTR1 mutations act heterogeneously in modifying RAS-MAPK signalling, similar to variants causing dominant NS." (PMID 35840934, 2022). "Seven years after identification of SMARCB1 as a causal entity, a second 22q gene LZTR1 was identified as a cause of schwannomatosis." (PMID 35361920, 2022). "To understand the effect of LoF LZTR1 variants in schwannomatosis patients further, we compiled a robust cohort of published schwannomatosis‐associated LoF LZTR1 variants for comparison with LZTR1 LoF variants seen in the non‐cancer gnomAD dataset." (PMID 35391499, 2022). "The two patients with multiple schwannomas were heterozygous for a pathogenic/likely pathogenic variant in the LZTR1 gene and are the first LZTR1-positive schwannomatosis patients reported in Asia." (PMID 35698239, 2022). "We collated published LOF LZTR1 variants identified in schwannomatosis patients and classified them according to current American College of Medical Genetics and Genomics/Association for Molecular Pathology/Association of Clinical Genomic Science guidelines." (PMID 35391499, 2022). "We report the first two Asian patients with schwannomatosis due to pathogenic or likely pathogenic LZTR1 variants." (PMID 35698239, 2022). "Mutations in LZTR1 (leucine-zipper-like transcriptional regulator 1) are associated with Noonan syndrome phenotypes and schwannomatosis." (PMID 36357925, 2022). "As it was known that LoF of the LZTR1 protein had been associated with human disorders such as schwannomatosis and Noonan syndrome, all nonsense variants and frameshift variants except c.2487dupA (in exon 21, the last exon) were assigned PVS1." (PMID 35391499, 2022). "In particular, there is an overlap between the LZTR1 variants seen in schwannomatosis and those seen in rare recessive forms of LZTR1‐associated Noonan syndrome, which is not a tumor predisposing condition." (PMID 35391499, 2022). "Like any other rare disease, one issue that hinders interpretation of the pathogenicity of LZTR1 variants detected in clinical laboratories is there are so few schwannomatosis cases, leading to an insufficient level of evidence." (PMID 35391499, 2022). "These frequencies indicate a strong association of LZTR1 with a schwannomatosis phenotype, supporting our use of PS4_M for these variants." (PMID 35391499, 2022). "To the best of our knowledge, we report the first two unrelated patients in Asia with schwannomatosis attributed to pathogenic or likely pathogenic LZTR1 variants." (PMID 35698239, 2022). "This, along with the incomplete penetrance of schwannomatosis, makes the classification of some predicted pathogenic LoF LZTR1 variants challenging." (PMID 35391499, 2022). "While the association of germline LZTR1 variants with human disease is still being elucidated, germline loss-of-function mutations in LZTR1 predispose to schwannomatosis and NS." (PMID 35840934, 2022). "We sought to investigate the risk of schwannomas in 22q11.2 deletion syndrome and the association with whole-gene deletion in LZTR1-associated schwannomatosis." (PMID 33879870, 2021). "We assessed the genetic testing results for LZTR1-associated schwannomatosis and the clinical phenotypes of patients with 22q11.2DS." (PMID 33879870, 2021). "The LZTR1 gene has been associated with schwannomatosis tumor predisposition and is located in a region that is deleted in the great majority (89%) of patients with 22q11.2 deletion syndrome (22q11.2DS)." (PMID 33879870, 2021). "Mutations in LZTR1 have been reported in diseases such as schwannomatosis and Noonan syndrome whereby loss of LZTR1 drives de-differentiation and proliferation of cells." (PMID 33432111, 2021).
schwannomatosis (continued). "Mutations in human LZTR1 have been linked with schwannomatosis, a form of neurofibromatosis, a neurological disorder associated with sleep problems, mental disabilities, and psychiatric disorders that can also be caused by mutation of the Nf1 gene." (PMID 32339168, 2020). "Approximately, one third of patients with Schwannomatosis are carriers of a germline pathogenic variant in LZTR1 (Leucin Zipper Transcription Regulator 1)." (PMID 32575496, 2020). "Genetic heterogeneity is observed in schwannomatosis since germline mutations in LZTR1 have also been identified in patients with the disease." (PMID 29779243, 2018). "In contrast to LZTR1-associated schwannomatosis, SMARCB1 mutations are probably less likely to predispose to unilateral vestibular schwannomas." (PMID 27921248, 2017). "Nevertheless, these studies serve to confirm that LZTR1 is a major schwannomatosis predisposition gene." (PMID 27921248, 2017). "Instead, germline mutations of either the SMARCB1 or LZTR1 tumour suppressor genes have been identified in 86% of familial and 40% of sporadic schwannomatosis patients." (PMID 27921248, 2017). "In addition, two families have beenreported where one member had schwannomatosis and another member developed aglioblastoma containing the LZTR1 mutation." (PMID 41522855, 2026). "LZTR1 pathogenic variants are mainly related to Schwannomatosis and Noonan syndrome." (PMID 40724954, 2025). "There is overlap between the variants seen in schwannomatosis and Noonan syndrome, although the variants seen in both conditions are normally inherited as autosomal dominant loss-of-function variants in LZTR1-SWN, while they are seen as part of a recessive inheritance pattern in Noonan syndrome." (PMID 41284083, 2025). "Schwannoma could co-occur in patients with INF2-related CMT, particularly in whom the germline schwannomatosis-predisposing variants such as LZTR1 simultaneously exist." (PMID 39857711, 2025). "In addition to SMARCB1 and LZTR1, other schwannomatosis predisposition genes located on chromosome 22q are likely to exist." (PMID 40794298, 2025). "Additionally, monoallelic LZTR1 variants are implicated in schwannomatosis, highlighting the gene’s diverse, tissue-specific impact on the RAS/MAPK pathway." (PMID 40332000, 2025). "Furthermore, LZTR1 loss-of-function mutations linked to Noonan syndrome and schwannomatosis underscore its critical role in maintaining RAS signaling homeostasis, providing a molecular rationale for therapeutic strategies targeting KRAS degradation." (PMID 40427667, 2025). "Additionally, pathogenic alterations in LZTR1 combined with specific somatic alterations cause Schwannomatosis." (PMID 41300834, 2025). "Phenotypes related to LZTR1 variants mainly include Noonan Syndrome and Schwannomatosis." (PMID 40724954, 2025). "Second, we show that the germline schwannomatosis-related LZTR1 variants may predispose the patients to hypertrophic changes." (PMID 39857711, 2025). "The molecular mechanisms underlying LZTR1 variants highlight its distinct contribution: biallelic inactivation drives global hyperactivation associated with NS, whereas monoallelic loss causes tissue-restricted phenotypes such as schwannomatosis." (PMID 40332000, 2025). "Schwannomatosis most likely constitutes a distinct clinical phenotype, as schwannomas are not frequently seen in Noonan syndrome, although the coexistence of NS and schwannomatosis in patients with LZTR1 pathogenic variants has been described." (PMID 39062695, 2024). "Patients with LZTR1 schwannomatosis exhibited 44 pathogenic variants, 51 likely pathogenic alterations, and 10 VUS which, as described, may be associated with loss-of-function mutations predisposing to schwannomatosis." (PMID 39062695, 2024). "Additionally, LZTR1 is considered a genetic susceptibility factor for schwannomatosis (#MIM 615670), a rare tumor predisposition syndrome that causes multiple schwannomas." (PMID 39062695, 2024).
schwannomatosis (continued). "LZTR1 variants have been associated with proliferative disorders, such as acute lymphoblastic leukemia in two NS patients, oligo-astrocytoma in one NS patient, and glioblastoma in two schwannomatosis patients." (PMID 39062695, 2024). "Additionally, two genetic variants in the LZTR1 gene, previously linked to schwannomatosis, were observed." (PMID 39000354, 2024). "Schwannomatosis-associated LZTR1 variants are mostly LOF changes located in almost every domain." (PMID 39062695, 2024). "According to previous in vitro mutational analyses, pathogenic LZTR1 mutations in patients with NS and schwannomatosis have been considered loss-of-function mutations, regardless of whether they are AD or AR hereditary forms." (PMID 39352760, 2024). "In rare cases, schwannomatosis caused by pathogenic variants in the Leucine-Zipper-Like Transcriptional Regulator 1 (LZTR1) gene may cause isolated VS that can be misdiagnosed as NF2." (PMID 37813009, 2023). "Loss‐of‐function (LoF) LZTR1 variants have been associated with schwannomatosis." (PMID 35391499, 2022). "Additionally, germline pathogenic variants in LZTR1 have been identified in patients with schwannomatosis and is thought to be a distinct entity as schwannomas are not frequently seen in NS." (PMID 35840934, 2022). "Additionally, the variant is rare and has been observed in a patient with schwannomatosis, which is associated with LZTR1 deficiency." (PMID 35806449, 2022). "The 396 potential disease‐causing LoF LZTR1 variants identified in 111,103 individuals in the non‐cancer gnomAD population were compared to the 64 LoF LZTR1 variants identified in 359 probands (17.8%) that were predicted to be pathogenic in the schwannomatosis cohort." (PMID 35391499, 2022). "Moreover, reducing maternal genetic interference allowed the detection of an affected homozygous fetus for LZTR1 gene variants causing schwannomatosis disease and wild-type status for the DVL2 gene." (PMID 36406136, 2022). "One reason that the allele frequency of some LZTR1 variants identified in many patients is higher than the expected value in the general population may be that the prevalence of LZTR1‐associated schwannomatosis is higher than previously thought." (PMID 35391499, 2022). "This means that if the effect of a whole-gene deletion were the same as a loss-of-function point variant, then, due to the 1 in 3–6,000 frequency of 22q11.2DS, we should expect to find one 22q11.2 deletion for every 12 to 25 LZTR1-associated schwannomatosis diagnoses." (PMID 33879870, 2021). "However, 116/425 (27.3%) of those meeting schwannomatosis criteria in Manchester (100/400 unrelated families [25%]) had a variant in LZTR1 (excluding class 3 variants of uncertain significance)." (PMID 33879870, 2021). "LZTR1 mutations are associated with Noonan Syndrome 10, Schwannomatosis-2, gastric cancer, ventricular septal defects, and deletion of the gene may be associated with DiGeorge syndrome." (PMID 30718897, 2019). "However, the frequency of somatic mosaicism of SMARCB1 or LZTR1 mutations in patients with schwannomatosis is as yet unclear." (PMID 29779243, 2018). "Although biallelic mutations of SMARCB1 or LZTR1 have been detected in the tumours of patients with schwannomatosis, the classical two-hit model of tumorigenesis is insufficient to account for schwannoma growth, since NF2 is also frequently inactivated in these tumours." (PMID 27921248, 2017). "Hence, in practice, tumorigenesis in LZTR1-associated schwannomatosis should follow a 5-hit/3-step model." (PMID 27921248, 2017). "The LP LZTR1 splice site variant (c.2407-1G > A) identified in our study has not been reported before, but a variant in the adjacent base (c.2407-2A > G) has been reported in Noonan syndrome patients (homozygous and one heterozygote in ClinVar) and in schwannomatosis patients." (PMID 35739278, 2022).